MZF1 (myeloid zinc finger 1)
Diseases named in the same sentence as MZF1 in open-access papers (continued):
Sharing a sentence is not in itself a finding about the gene and the disease.
lymphoma (5 papers, 2015 to 2022). A malignant (clonal) proliferation of B- lymphocytes or T- lymphocytes which involves the lymph nodes, bone marrow and/or extranodal sites. "Increased expression of IGF-IR in this lymphoma can be attributed, at least in part, to decreased expression of the transcription factors Ikaros isoform 1 (Ik-1) and myeloid zinc finger 1 (MZF1)." (PMID 31340850, 2019). "For instance, the transcription factors Ikaros isoform-1 (Ik-1) and myeloid zinc finger 1 (MZF1) are markedly decreased in this lymphoma." (PMID 27661006, 2017). "In this report, we were able to show that substantial decreases in the Ik-1 and MZF1 transcription factors play important roles in the pathogenesis of this lymphoma." (PMID 25884514, 2015). "In addition, overexpression of Ik-1 and MZF1 decreased the viability, proliferation, migration, and anchorage-independent colony formation of the lymphoma cells." (PMID 25884514, 2015). "Forced expression of Ik-1 or MZF1 in the lymphoma cells decreased IGF-IR mRNA and protein." (PMID 25884514, 2015). "However, we cannot completely exclude that the outcome of decreased expression of Ik-1 and MZF1 in this lymphoma is not only mediated through upregulation of IGF-IR because it is possible that these 2 transcription factors are involved in the regulation of other survival/oncogenic proteins." (PMID 25884514, 2015). "Also, transfection of Ik-1 and MZF1 was associated with decreased cell viability, proliferation, migration, and anchorage-independent colony formation of NPM-ALK+ T-cell lymphoma cells, asserting the tumor-suppressing impact of Ik-1 and MZF1 in this lymphoma." (PMID 25884514, 2015). "Forced expression of Ik-1 and MZF1 significanty decreased the activity of the IGF-IR gene promoter and downregulated IGF-IR mRNA and protein levels in these lymphoma cells." (PMID 25884514, 2015). "Although further analysis is required to support this idea, we cannot completely rule out that Ik-1 and MZF1 act as tumor suppressors in this lymphoma through targeting the expression of IGF-IR and IRS-1." (PMID 25884514, 2015).
triple-negative breast carcinoma (5 papers, 2016 to 2025). An invasive breast carcinoma which is negative for expression of estrogen receptor (ER), progesterone receptor (PR), and human epidermal growth factor receptor 2 (HER2). "The acidic domain of MZF1 is involved in its association with Elk1 in triple negative breast cancer." (PMID 31963147, 2020). "Moreover, a high level of MZF1 in triple-negative breast cancer cell lines Hs578T and MDA-MB-231 is associated with a mesenchymal phenotype with increased cell migration and invasion, which is mediated via insulin-like growth factor receptor (IGF1)." (PMID 31963147, 2020). "In triple-negative breast cancer cells, MZF1 activation can maintain the mesenchymal phenotype by interacting with Elk1 at the promoter region of IGF1R." (PMID 31963147, 2020). "Recently, the MZF1/Elk-1 complex has been identified as mediator of protein kinase C alpha (PKCα) expression in triple-negative breast cancer, which induces cell migration and invasion of triple negative breast cancer cells and poor outcome." (PMID 28435519, 2017).
leukemia (4 papers, 2009 to 2025). A malignant (clonal) hematologic disorder, involving hematopoietic stem cells and characterized by the presence of primitive or atypical myeloid or lymphoid cells in the bone marrow and the blood. "In the early stages of research, MZF1 was primarily studied for its role in hematopoietic differentiation and leukemia." (PMID 40655141, 2025). "In the context of leukemia, MZF1 was found to inhibit the differentiation of hematopoietic stem cells by suppressing the activity of the CD34 or c-myb promoters, thereby impeding differentiation and facilitating the emergence of a leukemia-like phenotype." (PMID 40655141, 2025). "Sp1 drives basal Axl transcription in solid cancer, but MZF-1 and AP-1 also drive Axl expression in leukemia cells." (PMID 35740998, 2022). "The following sections summarize the eight top-ranked genes in some of the major drug classes (FLT3, CASP8AP2, L2HGDH, MNT, BAZ2B, MZF1, BEX2, and SMARCA4) that are highly likely to have notable biological significance in leukemia." (PMID 29298978, 2018). "Sixteen of the corresponding transcription factors are of particular interest, as they are housekeeping genes or show a direct link to hematopoiesis, tumorigenesis or leukemia (e.g. GATA-1/2, PU.1, MZF-1)." (PMID 19587786, 2009).
neuroblastoma (4 papers, 2020 to 2025). Neuroblastoma (NB) is the most common solid, extracranial childhood tumor. "Targeting the YY1/MZF1 axis to reduce aerobic glycolysis led to a reduced tumorigenesis and aggressiveness of neuroblastoma, and thus represents a novel therapeutic target." (PMID 38893192, 2024). "Transcription factors YY1 and MZF1 are thought to play a critical role in the regulation of aerobic glycolysis in neuroblastoma, and thus have been targeted in a novel therapeutic approach." (PMID 38893192, 2024). "The authors developed a cell-penetrating peptide (MZF1-uPEP) to disrupt the interaction between YY1 and MZF1, which consequently inhibits the transcriptional activation of genes involved in aerobic glycolysis in neuroblastoma cells." (PMID 38893192, 2024). "In neuroblastoma (NB), myeloid zinc finger 1 (MZF1) and MZF1 antisense RNA (MZF1-AS1) are transcriptional regulators of proline synthesis and NB progression." (PMID 34825974, 2021). "Recent findings further suggest that the transcription factor myeloid zinc finger 1 (MZF1) can upregulate ALDH18A1 expression, and that elevated proline levels may contribute to the aggressive phenotype of neuroblastoma (NB) cells." (PMID 41200384, 2025).
pancreatic cancer (4 papers, 2020 to 2023). "High expression levels of HSP90AA1 and HSP90AB1 (associated with a low MZF1 expression scenario) were significantly correlated with poorer prognosis of patients suffering from pancreatic cancer." (PMID 36982267, 2023). "We showed that high expression of SCAN-TFs (SCAND1, SCAND2, and MZF1) were predictive biomarkers of enhanced prognoses for patients suffering from pancreatic cancer and head and neck cancers." (PMID 36982267, 2023). "Of note, high RNA expression of SCAND2, SCAND1, and MZF1 correlated with enhanced prognoses of pancreatic cancer and head and neck cancers." (PMID 36982267, 2023). "Kaplan–Meier analysis showed high expression of SCAND1 and MZF1 to correlate with better prognoses in pancreatic cancer and head and neck cancers, although with poorer prognosis in kidney cancer." (PMID 36552758, 2022). "MZF1 and SCAND1 high expression correlated with better prognoses in patients suffering from pancreatic cancer and head and neck cancers, suggesting that elevated SCAND1-MZF1 co-expression could inhibit EMT and invasive phenotypes in cancer." (PMID 36552758, 2022).
prostate tumor (4 papers, 2019 to 2022). "Regarding EMT drivers, both SCAND1 and MZF1 expression negatively correlated with CTNNB1 expression in prostate tumor specimens." (PMID 36552758, 2022). "The ability of an endogenous inhibitor, the zinc fingerless SCAND1 factor, to bind the promoter and repress the transcription of MZF1 suggests a potential mechanism for prostate tumor suppression." (PMID 31181782, 2019).
acute myeloid leukemia (3 papers, 2013 to 2023). Acute myeloid leukemia (AML) is a group of neoplasms arising from precursor cells committed to the myeloid cell-line differentiation. "Exceptionally, SCAND2 and MZF1(ZSCAN6) gene expression was higher in acute myeloid leukemia (LAML), while the expression levels of HSP90AA1 and HSP90AB1 genes were lower, compared with paired normal tissues." (PMID 36982267, 2023). "These include many transcription factor binding sites that are commonly functional in myeloid promoters including PU.1, SP1, myeloid zinc finger protein (MZF1), nuclear factor kappa B (NF-κB) or p50, octamer factor binding sequences (OCT) and acute myelogenous leukemia (AML1)." (PMID 23840844, 2013).
chronic myeloid leukemia (3 papers, 2016 to 2022). "MZF1 was firstly isolated from a cDNA library made from a patient with chronic myelogenous leukemia." (PMID 35350980, 2022). "MZF1 was first isolated from the peripheral blood from a patient with chronic myeloid leukemia and was described as a novel zinc finger protein involved in transcriptional regulation of hematopoietic development." (PMID 31963147, 2020). "MZF1 was originally isolated from chronic myeloid leukemia and was shown to be involved in hematopoietic differentiation due to its ability to control the expression of genes involved in hematopoiesis such as CD34 and MYB." (PMID 31963147, 2020). "MZF-1, a transcription factor of Krüppel family proteins, was originally cloned from the cDNA library of chronic myeloid leukemia." (PMID 27259238, 2016).
endometrial cancer (3 papers, 2016 to 2022). Primary or metastatic malignant neoplasm involving the endometrium (mucous membrane that lines the endometrial cavity). "PAX2 overexpression in endometrial cancer was regulated by promoter hypermethylation via the transcription factor MZF1." (PMID 27764784, 2016). "The overexpression of PAX2 in endometrial cancer is regulated by promoter hypermethylation and the transcription factor MZF1." (PMID 27764784, 2016).
myeloid leukemia (3 papers, 2016 to 2021). A clonal proliferation of myeloid cells and their precursors in the bone marrow, peripheral blood, and spleen. "In addition, Hoxa9 and Mzf1 involved in development of myeloid leukemia were up-regulated, while genes associated with differentiation, including Pax5 and Sox4, were down-regulated in both DKI and Dnmt3aR878H/+ groups." (PMID 31703632, 2019).
prostate adenocarcinoma (3 papers, 2019 to 2023). "Consistent with this, gene expression of SCAND2, SCAND1, and MZF1 was negatively correlated with HSP90 gene expression in prostate adenocarcinoma." (PMID 36982267, 2023). "In prostate adenocarcinoma specimens, the expression of MZF1 was positively correlated with both SCAND1 and SCAND2 RNA expression." (PMID 36982267, 2023). "MZF1 high expression is a poorer prognosis marker for patients suffering from prostate adenocarcinoma." (PMID 36552758, 2022). "Moreover, high expression of MZF1 correlated with poorer prognosis in prostate adenocarcinoma (bottom)." (PMID 36552758, 2022). "We showed that SCAND1 and MZF1 are mutually inducible, localized in heterochromatin with HP1γ, spatially co-localized in cancer cells in vitro, and coordinately expressed in many cases of clinical prostate adenocarcinomas." (PMID 36552758, 2022). "Next, we examined whether SCAND1 and MZF1 expression levels were correlated in clinical prostate adenocarcinoma specimens." (PMID 36552758, 2022). "Indeed, SCAND1 and MZF1 expression was significantly correlated in prostate adenocarcinomas, indicating that these SCAN domain proteins are consistently co-expressed." (PMID 36552758, 2022). "HSP90AA1 gene expression was negatively correlated with the gene expression of MZF1(ZSCAN6), SCAND1, SCAND2, and HSF4 in prostate adenocarcinoma specimens." (PMID 36982267, 2023). "Consistently, the co-expression analysis in TCGA PanCancer Atlas revealed that SCAND1 and MZF1 expression was negatively correlated with EMT driver genes, including CTNNB1, ZEB1, ZEB2 and TGFBRs, in prostate adenocarcinoma specimens." (PMID 36552758, 2022). "Co-expression correlation was found between MZF1 and CDC37 in CRPC patient samples (Spearman’s rank correlation score: 0.78) and in prostate adenocarcinoma patient samples (Spearman’s correlation: 0.41)." (PMID 31181782, 2019).
T-cell lymphoma (3 papers, 2015 to 2025). "Overexpression of MZF1 significantly inhibits the proliferation, migration, and clonogenic ability of T-cell lymphomas." (PMID 40655141, 2025). "Ik-1 and MZF1 also abrogated anchorage-independent colony formation of NPM-ALK+ T-cell lymphoma cells." (PMID 25884514, 2015). "We used Western blotting to screen the expression of Ik-1 and MZF1 proteins in 4 NPM-ALK+ T-cell lymphoma cell lines (Karpas 299, SR-786, DEL, and SUP-M2) as well as in normal human T lymphocytes." (PMID 25884514, 2015). "Compared with their expression in normal human T lymphocytes, the transcription factors Ik-1 and MZF1 are markedly decreased in NPM-ALK+ T-cell lymphoma cell lines and lymphoma tumors from patients." (PMID 25884514, 2015). "Our results provide novel evidence that the aberrant decreases in Ik-1 and MZF1 contribute significantly to the pathogenesis of NPM-ALK+ T-cell lymphoma through the upregulation of IGF-IR expression." (PMID 25884514, 2015). "Our data show that the transcription factors Ikaros isoform 1 (Ik-1) and myeloid zinc finger 1 (MZF1) have lower expressions in NPM-ALK+ T-cell lymphoma cell lines and human tumors relative to T lymphocytes." (PMID 25884514, 2015). "Screening studies showed substantially lower levels of the transcription factors Ikaros isoform 1 (Ik-1) and myeloid zinc finger 1 (MZF1) in NPM-ALK+ T-cell lymphoma cell lines and primary tumor tissues from patients than in human T lymphocytes." (PMID 25884514, 2015). "We performed a series of cellular assays to test the biological impact of forced expression of Ik-1 and MZF1 in NPM-ALK+ T-cell lymphoma." (PMID 25884514, 2015). "Thus, we resorted to using Western blotting to analyze the expression of Ik-1 and MZF1 in protein extracts from 15 ALK+ T-cell lymphoma patient tumor sections." (PMID 25884514, 2015). "In addition, Ik-1- and MZF1-induced downregulation of IGF-IR was assoicated with decreased NPM-ALK+ T-cell lymphoma viability, proliferation, migration, and anchorage-independent colony formation." (PMID 25884514, 2015). "To examine the expression of Ik-1 and MZF1 proteins in formalin-fixed and paraffin-embedded ALK+ T-cell lymphoma tissues from patients, we initially attempted using immunohistochemical (IHC) staining." (PMID 25884514, 2015).
breast tumors (2 papers, 2016 to 2024). "This process involves the poly-SUMOylation of myeloid zinc finger-1 (MZF1) at K23 directs MZF1 phosphorylation at S27 to further mediate invasive ERBB2 signaling in breast tumors." (PMID 39127633, 2024).
esophageal cancer (2 papers, 2020 to 2022). A primary or metastatic malignant neoplasm involving the esophagus. "In human esophageal cancer cell lines, phosphorylation of MZF1 serine 27 by CK2 initiates EMT by inducing the transcription of N-cadherin during the EMT-inducing switch from E-cadherin to N-cadherin." (PMID 31963147, 2020). "Interestingly, a recent study in human esophageal cancer cell lines demonstrated that phosphorylation of MZF1 serine 27 by constitutively active casein kinase 2 (CK2), which is often upregulated in cancers, mediates their epithelial to mesenchymal transition by inducing the expression of N-cadherin." (PMID 31963147, 2020). "CK2 phosphorylates MZF1 at Ser27 in human esophageal cancer cell lines and HEK293 cells, thereby stabilizing MZF1 and inducing N-cadherin transcription." (PMID 36009534, 2022).
kidney cancer (2 papers, 2022 to 2023). Primary or metastatic malignant neoplasm involving the kidney. "On the other hand, SCAND1 and MZF1 high expression correlated with poor prognosis in patients suffering from kidney cancer." (PMID 36552758, 2022).
liver cancer (2 papers, 2014 to 2021). An epithelial or non-epithelial malignant neoplasm that arises from the liver. "MZF1 is reported to function as a tumour promoter and is expected to facilitate cancer development, such as colorectal, lung and liver cancers." (PMID 33533172, 2021). "Eight modules are both CNV-TF regulated and CNV-gene enriched, and among these eight CNV-TFs, YY1, MZF1, DAND5, NFYB, ESR1 have been reported in liver cancer development and metastasis." (PMID 24897108, 2014).
non-small cell lung carcinoma (2 papers, 2025). A group of at least three distinct histological types of lung cancer, including non-small cell squamous cell carcinoma, adenocarcinoma, and large cell carcinoma. "In non-small cell lung cancer, FTO has been demonstrated to enhance tumor proliferation through multiple m6A-dependent mechanisms, including activation of KRAS signaling and upregulation of USP7 and MZF1." (PMID 39773744, 2025).
ovarian carcinoma (2 papers, 2016 to 2020). A malignant neoplasm originating from the surface ovarian epithelium. "MZF1 has been shown to serve as a transcription factor targeting excision repair cross-complementation group 1, which was involved in the development of drug resistance of human ovarian cancer." (PMID 32929338, 2020).
thyroid cancer (2 papers, 2015 to 2019). "The mutated TF MZF1 could negatively regulate target gene GAS1, which was also suppressed by MIR34A, to cause the proliferation and suppress the apoptosis of thyroid cancer cells." (PMID 31126066, 2019).
uterine carcinosarcoma (2 papers, 2023 to 2025). A usually aggressive malignant neoplasm arising from the uterine corpus and less often the cervix. "Our findings revealed that among TCGA datasets, the most prevalent alteration of the MZF1 gene was observed in Uterine Carcinosarcoma, with alteration frequencies exceeding 5%." (PMID 40655141, 2025).
Arrhythmogenic right ventricular dysplasia (1 paper, 2019). "Our results might support these findings, since the probe cg08897188 has a specific region that is able to bind MZF1 (Myeloid zinc finger 1 factors), which are associated with arrhythmogenic right ventricular dysplasia or cardiomyopathy (ARVD/C) with a similarity score of 0.992." (PMID 30813608, 2019).
autoimmune thyroid disease (1 paper, 2025). Inflammatory disease of the thyroid gland due to autoimmune responses leading to lymphocytic infiltration of the gland. "In KIRC, MZF1 acted as a positive regulator in antigen binding, negative regulation of lymphocyte-mediated immunity, antigen processing and presentation of peptide antigens, graft-versus-host disease, and autoimmune thyroid disease." (PMID 40655141, 2025).
B-cell acute lymphoblastic leukemia (1 paper, 2024). A neoplasm of lymphoblasts committed to the B-cell lineage, typically composed of small to medium-sized blast cells. "Several transcription factors increase mTOR transcription including sirtuin 1 (SIRT1), myeloid zinc finger 1 (MZF1), and Nrf2 while Ikaros represses mTOR transcription in B cell acute lymphoblastic leukemia." (PMID 38270460, 2024).
cervical clear cell carcinoma (1 paper, 2023). "Herein, we used comparative analysis to screen out genes with large differences in expression between HPV-negative and HPV-positive cervical clear cell carcinoma patients, including ALKBH7, MYCBP, MZF1, RNF207, RRS1, and TUSC2." (PMID 37654657, 2023).
colorectal tumors (1 paper, 2014). "MZF1 upregulates Axl and both genes positively correlate with colorectal tumors, where MZF1 induces invasion and metastasis." (PMID 25344858, 2014).
endothelial dysfunction (1 paper, 2022). In vascular diseases, endothelial dysfunction is a systemic pathological state of the endothelium (the inner lining of blood vessels) and can be broadly defined as an imbalance between vasodilating and vasoconstricting substances produced by (or acting on) the endothelium. "Wingless-type family member 5 (WNT5A), myeloid zinc finger 1 (MZF1), and lysine methyltransferase 8 (SETD8) have also been reported to elevate inflammatory factor levels and activate the nuclear factor kappa B (NF-κB) pathway to induce endothelial dysfunction." (PMID 35350980, 2022).
glioblastoma multiforme (1 paper, 2022). "Taken together, these findings suggest that CTD may be useful for the treatment of glioblastoma by inhibiting the expression of MZF1." (PMID 36499054, 2022). "Myeloid zinc finger 1 (MZF1), also known as zinc finger protein 42, is a zinc finger transcription factor, belonging to the Krüppel-like family that has been implicated in several types of malignancies, including glioblastoma multiforme (GBM)." (PMID 36499054, 2022).